EGFR (epidermal growth factor receptor)
Diseases named in the same sentence as EGFR in open-access papers (continued):
Sharing a sentence is not in itself a finding about the gene and the disease.
lung cancer (continued). "Previous studies indicated that MALT1 was required for the EGFR- and TNF-α/NF-κB signaling-induced IL-6 production in lung cancer progression." (PMID 33802402, 2021). "Pulmonary LELC had better prognosis, and previous studies also have discovered that classic lung cancer oncogenic drivers including KRAS, EGFR, BRAF, ALK, and ROS1 were limitedly involved in tumorigenesis and progression of pulmonary LELC." (PMID 34221995, 2021). "In the differentially expressed genes, we focused on EGFR and LINC00240 (lncRNA) because EGFR known as one of the master regulators in lung cancer is direct target of miR-7-5p." (PMID 33422052, 2021). "Furthermore, 6b emerged as the most promising anti-EGFR inhibitor with a great effect on gefitinib-resistant H1975 lung cancer cells, decreased oxidative stress and altered mitochondrial membrane potential leading to apoptosis and induced cell cycle arrest in A549 lung cancer cells at G phase." (PMID 33803355, 2021). "Here, we identified miR-185-3p as a significantly downregulated microRNA responsible for acquired EGFR TKI resistance in cells and patients with lung cancer." (PMID 34368128, 2021). "Some lung cancer‐related genes, such as EGFR, ALK, and KRAS, are usually used for targeted NGS in early‐stage lung cancer." (PMID 33200540, 2021). "Furthermore, the combination of EGFR-TKI and a β-catenin inhibitor suppressed the development of these adaptive persisters and improved overall survival of mouse tumor xenograft models, suggesting that combined EGFR and β-catenin inhibition might be a promising strategy for EGFR-mutant lung cancer." (PMID 34071428, 2021). "In this study, we revealed a novel mechanism of BASP1 in promoting lung cancer malignancy: BASP1 enriches EGFR in lipid rafts and enhances EGFR signaling by reducing CBL-dependent EGFR ubiquitination." (PMID 33042262, 2020). "A 55-year-old male lung cancer patient with cT3N1M1a, Stage IVA, EGFR (−), ROS1 (+) adenocarcinoma presented with a pleural effusion and was treated with crizotinib 250 mg twice daily and referred to our department." (PMID 32438645, 2020). "During the current study, NTR enzyme-responsive nanoparticle Nb@IC-NPs was constructed by combination of anti-EGFR nanobody with photosensitizer IR1048MZ and Cat, which were used for NIR-II/PA imaging and PDT of lung cancer." (PMID 33292202, 2020). "In 60 patients with lung cancer, using 2 CTC per 7.5 mL blood as cutoff value, the positive rates of EGFR, Vimentin and FA magnets used alone and in combination were 65.0%, 33.3%, 93.3% and 100%, respectively." (PMID 32336066, 2020). "Previous studies have showed that miRNA-7 down-regulates the expression of EGFR and key modulators of the Akt pathway including IRS-1 and IRS-2 in glioblastoma, breast, cervical and lung cancer, which led to decreased cell survival and proliferation." (PMID 32592373, 2020). "We found a marked increase in metastasis following intracardiac injection of EGFR-mutant PC9, HCC827, and HCC4006 lung cancer cells that were primed by co-culture with MSCs versus those grown in the absence of MSC-induced priming." (PMID 33119681, 2020). "Among identified pathways, we highlight the EGFR, FGFR1, KRAS, and PI3K-AKT signaling, and other well-known lung cancer pathways, such as MAPK and mTOR." (PMID 32726984, 2020). "In this study, mesoporous silica nanoparticles (MSN) were functionalised with EGFR targeting aptamers (MSN-AP) to recognise and bind to A549 lung cancer cell-derived EVs in both static and rocking flow conditions." (PMID 33143170, 2020).
lung cancer (continued). "This high EGFR mutation rate highlights the negative impact of not performing EGFR mutation testing and underscores the urgent need for broader discussion regarding the incorporation of molecular testing and targeted therapy for lung cancer in the Brazilian public and private healthcare systems." (PMID 32714871, 2020). "During the course of EGFR TKI treatment, survival lung cancer cells became insensitive and acquired enhanced NF-κB activity concomitantly." (PMID 33014814, 2020). "To conclude, NIR-II/PA imaging-guided PDT nanoparticles Nb@IC-NPs were constructed by combining anti-EGFR Nb with photosensitizer IR1048MZ and Cat for therapy of lung cancer." (PMID 33292202, 2020). "EGFR is commonly amplified in OSCC and has been shown to interact with ceramide in the development of cigarette smoke-induced lung cancer in mice." (PMID 32082486, 2020). "Published data have shown that epidermal growth factor receptor (EGFR) and anaplastic lymphoma kinase (ALK), molecules for first-line target therapy, improve prognosis for patients with lung cancer." (PMID 32433714, 2020). "Awareness of newer prognostic factors might provide a potential direction for further improvement in treatment for EGFR-mutated non–small-cell lung cancer, especially adenocarcinoma, but no study has focused on hematologic and inflammatory markers in EGFR-mutant lung adenocarcinoma." (PMID 32702917, 2020). "For example, IQGAP3 knockdown inhibited proliferation and ERK activity in cultured epithelial cells; IQGAP3 was also found to activate EGFR–ERK signaling and, thus, promote the metastasis of lung cancer cells." (PMID 33519444, 2020). "As expected, the Japanese population had higher rates of EGFR and ALK-positive lung cancer (31 and 6%, respectively in 2015–2017)." (PMID 33704175, 2020). "A direct link between the epidermal growth factor receptor (EGFR) and PD-L1 expression via NF-κB has been described in non-small-cell lung cancer (NSCLC), the most common lung cancer." (PMID 33324403, 2020). "Besides EGFR T790M, other resistance mutations can only be detected by the UltraSEEKTM Lung Panel (in BRAF, ERBB2, KRAS and PIK3CA, as well as EGFR C797S) and could be are useful for treatment decision making for lung cancer patients." (PMID 33081150, 2020). "Aberrant changes in KRAS, EGFR, ALK have been recognized as key drivers of lung cancer, and are frequently identified in LUAD." (PMID 32855362, 2020). "In network analysis, the hub targets of cinobufotalin injection against lung cancer were identified as VEGFA, EGFR, CCND1, CASP3, and AKT1." (PMID 32148531, 2020). "Nevertheless, when compared with existing markers of lung cancer, the sensitivity and specificity for Cyfra 21-1 were 43% and 89%, for CEA they were 57% and 92%, for SCC they were 75% and 90%, and for EGFR they were 71% and 80%, respectively." (PMID 32230883, 2020). "Histologic transformation from non-small cell to small cell lung cancer has been reported as a resistance mechanism to targeted therapy in EGFR-mutant and ALK fusion-positive lung cancers." (PMID 32802958, 2020). "Therefore, to test whether EGFR-TKI treatment affects CEA expression pattern and dissemination ability of lung cancer cells harboring EGFR mutations, we treated EGFR-mutant HCC827 (delE746_A750) lung adenocarcinoma cells with increasing concentrations of gefitinib." (PMID 32034239, 2020). "Epidermal growth factor receptor (EGFR) is a major driver of lung adenocarcinoma, which is essential to lung cancer cell proliferation." (PMID 33138822, 2020). "The GSE72526 was a dataset using microRNA to predict ALK, EGFR, and KRAS statuses in lung cancer patients and to use ALK, EGFR, and KRAS as biomarkers to diagnose lung cancer." (PMID 31976313, 2020). "EGFR and FGFR1 appear to work together to increase tumorgenicity in lung cancer, and active FGFR1 can increase resistance to EGFR targeted therapies." (PMID 32209086, 2020).
lung cancer (continued). "Molecular testing for EGFR, ALK, and ROS1 is currently mandatory for patients with lung cancer in routine practice." (PMID 32196518, 2020). "Our studies showed that BASP1 knockdown decreased calcium influx in lung cancer cells treated with EGF, suggesting that BASP1 enhanced EGFR signaling and calcium influx to increase cell migration." (PMID 33042262, 2020). "Herein, a multi-functional nanoplatform Nb@IC was designed by using of anti-EGFR Nb combined with photosensitizer and catalase (Cat) to improve tumor hypoxia, enhancing the therapeutic efficacy of PDT of IR1048MZ in lung cancer." (PMID 33292202, 2020). "Reportedly, in lung cancer cells, arsenic exposure upregulates the levels of heparin binding-EGF (an EGFR ligand) and stimulates an activating phosphorylation of EGFR (p-EGFR at Tyr 1173)." (PMID 32695675, 2020). "Genetic mutations in Ki-ras2 Kirsten rat sarcoma viral oncogene homolog (KRAS), epidermal growth factor receptor (EGFR), B-RAF (BRAF), and phosphatidylinositol 3-kinase (PI3K) signaling oncogenic pathways have been identified in lung cancer." (PMID 32984047, 2020). "Deng and colleagues reported that forced expression of TUSC2 enhanced the antitumour activity of cisplatin in human lung cancer cells; TUSC2 restoration sensitized lung cancer cells to treatment with EGFR inhibitors." (PMID 31973107, 2020). "Silencing MUC1-C in H1975/EGFR(L858R/T790M) cells suppresses AKT signaling pathway, and inhibits cell proliferation of lung cancer." (PMID 32807223, 2020). "Among the 54 established PDX models, 12 were developed from FGFR-driven tumours resistant to erdafitinib, 9 from EGFR-mutant osimertinib resistant tumours and 4 from ALK-rearranged lung cancers resistant to lorlatinib." (PMID 32964129, 2020). "CDK7 inhibition has previously been reported to downregulate EGFR in high-grade glioma and PLK2 in a lung cancer cell line." (PMID 32155786, 2020). "In EGFR-mutant lung cancer, LINC00460 promotes EGFR-TKI resistance, and patients with high LINC00460 expression who receive gefitinib therapy have a lower five-year OS rate than do patients with low LINC00460 expression." (PMID 33193668, 2020). "Since both of these mutations work hand in hand, previous and recent research suggests co-targeting both EGFR and c-MET in lung cancer." (PMID 32316322, 2020). "The positive staining ratios of EGFR phosphorylation (Y1068) and PKM2 were significantly higher in most cases of lung cancer than in paired normal tumor-adjacent lung tissues; and HB-EGF expression levels strongly correlated with p-EGFR expression levels." (PMID 32695675, 2020). "A dual blockade of EGFR and MET can significantly inhibit the proliferation several carcinoma cells, including lung cancer cells, head and neck cancer cells, and colon cancer cells." (PMID 32070026, 2020). "Since the FGFR mediates EGFR signaling, the efficacy of FGFR-TKIs in cancer treatment was investigated using C. elegans tumor models and lung cancer cell lines." (PMID 33092268, 2020). "In lung cancer cell lines, we also observed that EGFR exon 19 deletion NSCLC cell line showed a lower survival rate than EGFR wild‐type ones after 5 μM cisplatin treatment." (PMID 31875360, 2020). "In summary, our data identified a crucial oncogenic role of Mig-6 in the survival of EGFR-TKI-resistant lung adenocarcinoma and we suggest targeting Mig-6 to overcome EGFR-TKI resistance in lung cancer." (PMID 32552717, 2020). "Currently, all clinical trials of first-line ICIs, either single- or dual-agent, have excluded EGFR-mutant and ALK-rearranged lung cancers but included patients with RET-rearranged lung cancers." (PMID 32295619, 2020). "The expression levels of EGFR and CHKA, and the phosphorylation of EGFR and MAPK were reduced in lung cancer cells with FAM83A knockdown." (PMID 33266425, 2020).
lung cancer (continued). "Most commercial laboratories offer limited or no testing for hereditary lung cancer variants, and no guideline has been established for the best way to manage unaffected carriers of variants associated with lung cancer, such as germline EGFR T790M, HER2 and YAP1 mutations." (PMID 32104210, 2020). "We also show that FGFR-TKIs exhibit anti-tumor effects on the EGFR-TKI-resistant, EGFR T790M-L858R-expressing lung cancer cells and nematode model." (PMID 33092268, 2020). "The EGFR/HER2 signaling pathway is frequently activated in many cancers, including hepatocellular carcinoma, lung cancer, colorectal cancer, and breast cancer, and plays a critical role in carcinogenesis and progression 29-32." (PMID 32398965, 2020). "On the other hand, silmitasertib combined with the EGFR inhibitor erlotinib produces a complete inhibition of the PI3K/Akt/mTORC1 pathway, inducing apoptosis in squamous carcinoma and lung cancer cells." (PMID 32626654, 2020). "In EGFR mutant lung cancer, cMet amplification and increased tumoral HGF expression are common mechanisms of both de novo and acquired resistance to EGFR TKIs." (PMID 32545260, 2020). "Of note, in vitro and in vivo tumor suppressive functions of CLU were also confirmed on lung cancers driven by two other important oncoproteins, namely mutant EGFR driven and EML4-ALK driven lung cancers." (PMID 33052230, 2020). "In lung cancer, the combined treatment with LDE225 and Erlotinib (an EGFR inhibitor) showed a reduction in cell invasion, migration, colony formation, proliferation, and induced apoptosis." (PMID 33396427, 2020). "Targeted drugs for lung cancer, mostly NSCLC, mainly include EGFR-tyrosine kinase inhibitors (EGFR-TKIs) and ALK-tyrosine kinase inhibitors (ALK-TKIs)." (PMID 33299643, 2020). "The advancement in genetics and molecular medicine, such as epidermal growth factor receptor (EGFR), tyrosine kinase inhibitors (TKI), and anaplastic lymphoma kinase inhibitors, contributed greatly to lung cancer therapies, particularly to NSCLC." (PMID 32281704, 2020). "Osimertinib, a third-generation epidermal growth factor receptor (EGFR)-tyrosine kinase inhibitor (TKI), can be used as second-line treatment for lung cancer patients harboring the T790M substitution." (PMID 33008313, 2020). "Arsenic exposure in lung cancer cells reportedly upregulates expression of the EGFR ligand, heparin binding-EGF (HB-EGF) and activates EGFR phosphorylation (p-EGFR at Tyr 1173)." (PMID 32695675, 2020). "Mechanistically, downregulation of LOC389641 was found to decrease EGFR, MET and STAT3 proteins expression in lung cancer cells." (PMID 33318313, 2020). "The combination of EAI045 with cetuximab, an antibody that blocks EGFR dimerization, renders the kinase sensitive to EAI045 and was effective in a mice model of lung cancer driven by EGFR(L858R/T790M)- and EGFR(L858R/T790M/C797S) mutations." (PMID 32549388, 2020). "In this frame, it has been shown that the physical interaction between CCDC6-RET and the EGFR facilitates signaling and reduces efficacy of RET kinase inhibition in a lung cancer cell line." (PMID 32326537, 2020). "In addition, low tumor mutational burden and the lack of CD8+ tumor-infiltrating lymphocytes in the tumor microenvironment in lung cancer with EGFR mutations may be possible explanations for the lack of efficacy of PD-L1 inhibitors." (PMID 33363040, 2020). "Previous studies have reported that the occurrence of EMT confers acquired resistance to EGFR-targeted therapy and that 14-3-3ζ promotes the EMT phenotype in lung cancer." (PMID 33123465, 2020). "EGFR‐activated STAT3, for example, is critical for lung cancer metastasis (Soon, Leong, Koh, & Tham, 2015)." (PMID 33304472, 2020).
lung cancer (continued). "Furthermore, the recombinant LZ-8 (rLZ-8) induced the degradation of epidermal growth factor receptor (EGFR) in a clathrin-mediated, endocytosis-dependent, and c-Cbl ubiquitination-dependent manner, which in turn, inhibited proliferation and promoted apoptosis of lung cancer cells." (PMID 32676028, 2020). "The main feature that characterizes these “niche” mutations is their low prevalence in the population of patients with lung cancer when compared with KRAS and EGFR." (PMID 32082488, 2020). "Despite the discovery of EGFR (epidermal growth factor receptor) gene alterations and development of targeted therapies which has revolutionized the treatment of NSCLC, the mortality of lung cancer has continued to increase over time." (PMID 32656988, 2020). "Despite the importance of NANOG in lung cancer progression and in regulating CSC properties, the relevance between NANOG with EGFR-TKI resistance is yet unclear." (PMID 32820157, 2020). "In lung cancers, for which ERLO is routinely used, EGFR protein levels and activity, that are crucial for ERLO efficacy, are never assessed before ERLO treatment." (PMID 31938054, 2020). "It has also been reported that suppression of PI3K‐AKT‐mTOR pathway was enhanced by combined targeting of EGFR and CK2 in lung cancer models relying on EGFR activity." (PMID 32672423, 2020). "As a well-known therapeutic onco-target, epidermal growth factor receptor (EGFR) has played an important role in the treatment of various tumors, such as lung cancer." (PMID 32079107, 2020). "HB-EGF expression were upregulated in As-T cells, lung cancer cell lines, and in most lung cancer tissue samples; and HB-EGF activated the EGFR/p-ERK/HIF-1α pathway and induced VEGF by regulating HIF-1α transcription." (PMID 32695675, 2020). "Dual targeting of epidermal growth factor receptor (EGFR) and human EGFR-related receptor 2 (HER2) is a proven approach for the treatment of lung cancer." (PMID 33374155, 2020). "In EGFR mutant lung cancer cells, H3K9 demethylation mediated upregulation of BCAT1 and subsequent metabolic reprogramming, which promotes TKI (lethal EGFR tyrosine kinase inhibitors) resistance through attenuating reactive oxygen species (ROS) accumulation." (PMID 32448308, 2020). "A total of 194 and 141 EGFR‐mutant non‐small cell lung cancer (NSCLC) patients treated with first‐ and second‐generation EGFR‐TKIs were examined in the CTONG0901 and GLCI cohorts, respectively." (PMID 32508032, 2020). "Trametinib is an MEK1 inhibitor for treating EML4-ALK-positive, EGFR-activated, and KRAS-mutant lung cancers." (PMID 32245216, 2020). "It was shown that GPRC5A interacts with the epidermal growth factor receptor (EGFR) thereby preventing its signaling and reducing proliferation of lung cancer cells." (PMID 32719397, 2020). "NRP1-dependent JNK signaling leads to the overexpression of EGFR and IGF1R, which induces resistance to BRAF (melanoma targeted therapy), HER2 (breast cancer targeted therapy) and MET (stomach and lung carcinomas therapy) inhibitors." (PMID 32766254, 2020). "This likely reflects autocrine EGFR stimulation, as supported by increased expression of EGF ligands such as epiregulin (EREG) in lung cancer cells." (PMID 30890751, 2019). "In BRAF wild-type lung cancer preclinical models, the biological active properties of single or combined therapies for BRAF (dabrafenib), pan-RAF (RAF265), MEK (trametinib), and EGFR/HER2 (lapatinib) were evaluated." (PMID 31652660, 2019). "Uncontrolled activity of the transmembrane receptor tyrosine kinase (RTK) epidermal growth factor receptor (EGFR) can function as oncogenic driver and target for precision medicine intervention in lung cancer cells." (PMID 31266248, 2019). "This is consistent with other studies reporting low TMB in EGFR, ALK, ROS1, or RET-driven lung cancers [30•], but higher in KRAS or BRAF." (PMID 31172347, 2019).